BCL2 (BCL2 apoptosis regulator)
Diseases named in the same sentence as BCL2 in open-access papers (continued):
Sharing a sentence is not in itself a finding about the gene and the disease.
colon carcinoma (continued). "In the colon cancer patient tissue BCL2 is often abnormally highly expressed, and higher frequencies of BCL2-positive cells are linked with lower overall rates of apoptosis." (PMID 33469000, 2021). "Since BCL2 was widely studied in colon cancer cells and was among the least regulated genes by gossypol, we therefore selected BCL2 mRNA as the internal reference for our qPCR analyses." (PMID 33723275, 2021). "Transfection of the NEU3 sialidase gene into colon cancer cells inhibited apoptosis and was accompanied by increased Bcl-2 and decreased caspase expression." (PMID 34064863, 2021). "Our study showed that BCL2 mRNA was the most stable among the mRNAs from 55 genes analyzed in human colon cancer cells treated with DMSO vehicle or various concentrations of gossypol." (PMID 33723275, 2021). "The level of Bax in the DMH group with induced colon cancer was higher than in the control group, whereas the level of Bcl-2 was significantly increased in the groups treated with DMH and MSC or only MSC (P<0.05)." (PMID 33604610, 2021). "This molecule triggers the intrinsic pathway of apoptosis by downregulating Bcl-2, Bcl-xL, survivin, and upregulating Bax, as evidenced in numerous tumor lines of gallbladder cancer, esophageal cancer, colon cancer, leukemia, and glioblastoma." (PMID 34208196, 2021). "The experimental results indicated that PSVII@MCP-CaP reduced Bcl-2 expression and increased Bax, Cleaved caspased-9 and Cleaved caspased-3 expression in drug-resistant colon cancer tissue." (PMID 34789268, 2021). "We further showed that BCL2 mRNA was the most stable among the 55 mRNAs in human colon cancer cells." (PMID 33723275, 2021). "It was reported that bacteria-extracted β-glucan induced apoptotic cell death in colon cancer, and upregulated apoptotic induced genes including Bax and Caspase-3 genes and down regulated Bcl-2 gene." (PMID 33917024, 2021). "This supported the other research that showed BmKn-2 induced apoptosis in human oral cancer cells and colon cancer cells through Bax up-regulation and Bcl-2 down-regulation expressions." (PMID 34359246, 2021). "In the present work, a series of novel isatin-indole conjugates (7a-j and 9a-e) was designed and synthesised as potential antiproliferative agents towards colon cancer cells with promising inhibitory activity against the anti-apoptotic Bcl2 and BclxL proteins." (PMID 33345633, 2021). "Previous experiments have reported a significant rise in the BAX/BCl2 ratio following the administration of myricetin in human hepatocarcinoma and human colon cancer." (PMID 33369440, 2020). "Interleukin stimulation slightly improved colonic cancer cell viability, weakly upregulating BCL2 and Ki67 in HCT116 and HT-29." (PMID 32512917, 2020). "The inhibition of Bcl2 expression and the increase in Bax level by CyCl thus provides a mechanistic basis of apoptosis induction by the compound in colon cancer cells." (PMID 32230772, 2020). "Gene expression analysis by qRT-PCR showed that treatment with CyCl decreased Bcl2 expression and increased Bax expression in colon cancer cells." (PMID 32230772, 2020). "Bcl2 has been reported to be overexpressed in colon cancer, and overexpression of Bcl2 or Bcl-xl suppresses apoptosis and promotes cell survival." (PMID 32230772, 2020). "The findings are also consistent with cellular apoptotic activities shown by increased caspase-3 activity and decreased Bcl-2 protein level in both colon cancer cell lines." (PMID 32825505, 2020).
colon carcinoma (continued). "One the other hand, high expression of NEIL1 promoted the cell viability and reduced the apoptosis, inducing the balance of Bax/Bcl-2 in the human colon cancer cells to be antiapoptotic." (PMID 32685496, 2020). "There have been reports of colorectal cancer cells treated with Ag NPs, and the down-regulation of Bcl-2 expression, which inhibited colon cancer proliferation, has also been recorded." (PMID 32120830, 2020). "We evaluated the association of hnRNPA2B1 with BCL2L1, BCL2, MDM2, cMYC, CD44, CDK6, cJUN, and TXNP in HCT116 colon cancer cells treated with 70 μg/ml of the crude extract." (PMID 33163396, 2020). "rhamnosus exert antitumorigenic effects against HT-29 colon cancer cells possibly through the indirect induction of Bcl-2 and Bak family." (PMID 32774810, 2020). "At the molecular level, A1874 is able to induce BRD4 protein degradation and the downregulation of BRD-dependent genes (c-Myc, Bcl-2 and cyclin D1) in colon cancer cells." (PMID 32978368, 2020). "Linc02418 promotes growth, mobility and invasion and inhibits apoptosis via targeting miR-34b-5p and Bcl-2 pathways in colon cancer." (PMID 33246471, 2020). "Subsequently, expression of genes encoding proliferation marker Ki67, anti-apoptotic proteins BCL-2 and BCL-xL, and cell cycle regulator p21CIP1/WAF1 in colon cancer cells stimulated with IL-4 or IL-13 was determined." (PMID 32512917, 2020). "It has also been reported that ASA induces apoptosis by increasing bcl-xl and bax while decreasing bcl-2 in colon cancer." (PMID 33217901, 2020). "Reported as an adaptor protein for RAS/MAPK, JAK/STAT, and PI3K pathways, CRKL led to the overexpression of apoptosis-inhibited gene BCL-2 in colon cancer." (PMID 33094104, 2020). "PPAR-γ ligands were previously shown to significantly induce apoptosis in colon cancer cells by suppressing the activity of NF-κB, which is a transcription factor of Bcl-2, and inhibiting the expression of antiapoptotic Bcl-2 proteins." (PMID 31354797, 2019). "Recent studies have demonstrated that combination treatment with MDM2 inhibitor and Bcl-2 inhibitor results in synergistic anti-tumor activity compared with the respective single-agent treatments in acute myeloid leukemia and colon cancer cells." (PMID 30816344, 2019). "Suppression of Bcl-2 level and up-regulation of Bax by curcumin has also been observed in other colon cancer cells such as HCT-116 and COLO-205 cells." (PMID 31108984, 2019). "Curcumin was found to regulate downstream apoptosis related genes (caspase 3, cytochrome C, Bax and Bcl-2) by suppressing PI3K/AKT pathway in human colon cancer cell lines, LoVo." (PMID 31108984, 2019). "Increasing the Bax/Bcl-2 ratio or inhibiting Bcl-2 expression, both markers of apoptosis, by treatment with bioactive compounds in colon cancer cells limited their growth." (PMID 31905929, 2019). "The ratio of autophagy-related genes, Beclin1 and Bcl-2, in adenine-treated colon cancer cells was increased in a dose-dependent fashion." (PMID 31611925, 2019). "Overall, 32.7% of CRC showed Bcl-2 positivity, out of which 20.6% of Bcl-2 expression was noted in left colonic tumors, 12.1% of Bcl-2 positivity was seen in right colonic tumors." (PMID 31754362, 2019). "It has been reported that endothelial cells incubated with IL-8 promotes higher levels of Bcl-2:Bax ratios, and therefore, we determined interrelation of Bax and IL-8 in prostate and colon cancer cells." (PMID 31673102, 2019). "A similar study has demonstrated that GE inhibits the viability of human colon cancer HT-29 cell via induction of apoptosis mainly through regulation of p21WAF1 and Bax/Bcl-2 expression." (PMID 31030484, 2019). "Further data should revel if the activity of Kaempherol is Bcl-2 specific or is an effect specific for colon cancer inhibition." (PMID 30857282, 2019).
colon carcinoma (continued). "Treatment of eupatorin in combination with doxorubicin in colon cancer simultaneously increased the Bax/Bcl-2 ratio, caspase-3 expression, and PARP cleavage and induced apoptotic cell death." (PMID 30597838, 2018). "It was found that colonic tumors of animals belonging to L. rhamnosus GG + celecoxib+DMH (Group V) had significantly (p < 0.05) down regulation of an anti apoptotic Bcl-2 expression compared with L.acidophilus + celecoxib+DMH (Group IV), L. acidophilus + L." (PMID 30424722, 2018). "Most cell lines exhibited higher, cumulative expression levels of BAK and BAX when compared to cumulative expression levels of anti-apoptotic BCL2 proteins, as previously observed in colon cancer cells." (PMID 29352235, 2018). "Several important colon cancer related genes, including well established targets of miR-15a, BCL2 and BMI1 as well as novel targets, YAP1 and DCLK1 contain binding sites for miR-15a in their 3’UTRs." (PMID 29416778, 2018). "It has been confirmed that the genes such as anti-apoptotic (B-cell lymphoma-2, Bcl-2) and pro-apoptotic (Bax) are important regulators of apoptosis in colon cancer cells." (PMID 29202800, 2017). "In this study, significantly increased apoptosis in association with up-regulation of Bax and down-regulation of Bcl-2 were observed in colon cancer cells treated with MG or GLOI silencing." (PMID 28903386, 2017). "Meanwhile, shikonin-induced depolarization of mitochondrial membrane potential was attenuated and decreased Bcl-2 or Bcl-xL expression also recovered with co-treatment with the antioxidants NAC or GSH in colon cancer cells." (PMID 29312593, 2017). "It has been confirmed that the genes such as anti-apoptotic (B-cell lymphoma-2, Bcl-2) and pro-apoptotic (Bax) are important regulators of apoptosis in colon cancer cell lines." (PMID 29202800, 2017). "Protein of bcl-2 of archival surgical resection specimens from 61 patients with colon cancer were stained with immunohistochemistry." (PMID 28978062, 2017). "Apoptosis was activated in human colon cancer cells by modifying the expressions of Bax, Bcl-2, XIAP, caspase-3, p21 and CDK2 proteins." (PMID 27628414, 2016). "Hesperidin induces human colon cancer SNU-C4 cell apoptosis as determined by a decrease in messenger RNA (mRNA) expression of bcl-2 and an increase of bax mRNA levels with an increase of caspase-3 expression and activity." (PMID 26194866, 2016). "To evaluate L3 clinical significance in colon cancer, we employed quantitative real-time RT-PCR (qRT-PCR) to assess the expression of L3 and its target gene p21, Bcl-2 and Bax at the mRNA levels in 30 colon cancers and normal tissues." (PMID 27835895, 2016). "As a result of reduced Bcl-2 expression and increased Bax expression by BG-4 treatment, the expression of active caspase-3 in human colon cancer cells were significantly increased by 125 μg/mL BG-4 treatment." (PMID 27628414, 2016). "Based on CCK-8 assays, we confirmed that overexpression of BCL2 reversed the inhibitory effects of miR-139-5p on drug resistance in colon cancer cells." (PMID 27244080, 2016). "Treatment of human colon cancer cells by 125 μg/mL led to increased Bax:Bcl-2 ratio indicating the potential use of BG-4 as anti-colon cancer therapeutic agent." (PMID 27628414, 2016). "In order to clarify the biological significance of L3 elevated levels in colon tumor tissues, we evaluated the expression levels of L3 target gene Bcl-2 and Bax." (PMID 27835895, 2016). "Colon cancer have higher levels of sumoylated MATα2, total MATα2, Ubc9 and Bcl-2 and higher MATα2 binding to the Bcl-2 P2 promoter." (PMID 26416353, 2015). "MATα2 is also SUMO-1 sumoylated in normal colon tissue and this is enhanced in colon cancer and higher protein levels of Ubc9, MATα2 and Bcl-2 all occur in the cancer tissues." (PMID 26416353, 2015).
colon carcinoma (continued). "We also observed that BV induced the increasing expression of DR downstream apoptotic proteins such as cleaved caspase-3, cleaved caspase-8, cleaved caspase-9 and Bax but decreased expression of Bcl-2 in colon cancer cells." (PMID 26561202, 2015). "The results demonstrate that the isolated SP containing plentiful fucose and sulfated group contents has the anticancer effect on colon cancer cells via regulation of Bcl-2/Bax signal pathway." (PMID 26417363, 2015). "In contrast to bortezomib, b-AP15 induces cell death independently of Bcl-2, Bax and Bak, exhibits anti-tumor activity in solid tumor models and shows greatest activity towards colon carcinoma and CNS lineage cells." (PMID 25286379, 2014). "Aspirin is also able to induce apoptosis by down-regulating Bcl-2 protein expression in colon cancer cells and human gastric epithelial cells." (PMID 24923427, 2014). "In the other colon cancer cell line, mRNA expression of BCL2 and ERBB4 JMa-1 was seen to be upregulated in the presence of WWOX." (PMID 24938873, 2014). "Our results supported a previous study that demonstrated the inducing of apoptosis of astaxanthin-rich Haematococcus pluvialis extract on HCT-116 colon cancer cells by the increasing of the ratio of Bax/Bcl-2 expression." (PMID 23509778, 2013). "For example; NRF2 has recently been shown to induce the expression of the anti-apoptotic BCL2 gene which is associated with poor prognosis in AML and colon cancer." (PMID 24029073, 2013). "G0S2 overexpression also augmented apoptosis in lung and colon cancer cells by interacting with Bcl-2, which in turn antagonized the formation of anti-apoptotic Bcl-2/Bax heterodimers." (PMID 23546556, 2013). "Conversely, in colon cancer, up-regulation of miR-365 is thought to repress tumor formation and maintenance by targeting the anti-apoptotic genes BCL-2 and cyclin D1." (PMID 24029073, 2013). "The proapoptotic effects of aspirin (5 and 10 mM) were further investigated in colon cancer cells by determining changes in expression in the survival proteins bcl-2 and survivin and induction of caspase-dependent PARP cleavage." (PMID 23110215, 2012). "In more than 60% of all colon cancer, Bcl-xL staining is more pronounced than in normal colon epithelium, whereas Bcl-2 expression was reported to be too low for detection by Northern blotting." (PMID 14520471, 2003). "Bispecific AS oligonucleotides targeting Bcl-xL and Bcl-2 have been shown to reduce colon cancer cell growth in vitro and in vivo." (PMID 14520471, 2003). "In both the uninvolved MIN mouse colonic epithelium and HT-29 colon cancer cells, nabumetone downregulated the anti-apoptotic protein, Bcl-2, with concomitant induction of apoptosis, suggesting a potential mechanism for colon cancer chemoprevention." (PMID 11355956, 2001). "Bcl‐2 is an antiapoptotic protein whose high expression may lead to abnormal proliferation of colon cancer cells." (PMID 39803233, 2025).
colon carcinoma (continued). "In addition, BCL-2 proteins have been reported to control cellular bioenergetics in colon carcinoma cells, and BCL-2 inhibition by VEN or WEHI-539 reduced mitochondrial ATP production at concentrations that did not induce cell death." (PMID 38961053, 2024). "The analysis of gene expression considered five genes associated with apoptosis—BCL2 (B-cell CLL/lymphoma 2), BCL2L1 (BCL2 Like 1), BCL2L2 (BCL2 Like 2), CASP3 (caspase 3), and CASP9 (caspase 9), and was carried out in human colon cancer cells exposed to the IC50 dose of BVR." (PMID 38732003, 2024). "They demonstrated that silencing of miR-210 upregulated Bcl-2 expression in colonic carcinoma." (PMID 36939902, 2023). "By promoting Bax, Caspase-9, and Caspase-3, inhibiting Bcl-2 protein expression, and regulating the Bax/Bcl-2 apoptotic signaling pathway in human colon cancer cells, ATL III inhibits cell proliferation and induces apoptosis in HCT-116 cells, producing anti-colon cancer effects." (PMID 37241729, 2023). "Moreover, the Bax/ Bcl-2 ratio increased remarkably hence, sensitizing colon cancer cells toward apoptosis." (PMID 37493814, 2023). "In addition, the combination therapy also significantly enhanced the expression of p21WAF1/CIP1, caspase 3 cleavage, and down-regulated the expression of bcl-xL, bcl-2, and surviving in rat colon tumor tissues." (PMID 38033490, 2023). "The identification of a regulator such as IMP3 could explain the molecular mechanism that allows the up-regulation of Bcl-2 antiapoptotic protein expression in colon cancer." (PMID 37024466, 2023). "Additionally, myricetin induced apoptosis in colon cancer cells through the Bax/Bcl-2-dependent pathway." (PMID 38026996, 2023). "In addition, studies found that NF-E2-related factor-2 (Nrf2) can mediate the apoptosis induced by allicin in colonic cancer cells, although Nrf2 is usually considered an anti-apoptotic factor that upregulates the anti-apoptotic protein Bcl-2." (PMID 35770084, 2022). "In AGS gastric cancer cells (AGS) as well as HT-29 colon cancer cells, we detected a statistically significant increase in cells expressing inactivated Bcl-2 after treatment with iodine-biofortified lettuce extracts, as compared to the control lettuce or negative control." (PMID 36296971, 2022). "Human colon cancer cells were also treated with various concentrations of glandless cottonseed coat extract and analyzed gene expression at the mRNA levels by qPCR using BCL2 mRNA as the internal reference and 1% DMSO treatment as the sample control." (PMID 35058516, 2022). "Similarly, fermented Pu-erh tea (Xiaguan bowl tea [X]) decreased Bcl2 gene expression in HT-29 colon cancer cells." (PMID 36364387, 2022). "Furthermore, the western and qRT-PCR results suggested PI3K, ERK1/2, Bcl2, and Bax were the potential targets in colon cancer treatment." (PMID 35815259, 2022). "Therefore, our results show that RUT promotes the apoptosis of colon cancer cell lines by up-regulating the expression of cleaved-Caspase3 and down-regulating the expression of Bcl-2." (PMID 35154453, 2022). "We ascertained that Bcl2 overexpression could support the survival of colon cancer cells upon DET treatment." (PMID 35563442, 2022). "Moreover, a deregulated Bcl-2 rheostat is often observed in human tumors, including lung and colon cancer." (PMID 34257274, 2021). "In addition, BAX changes the anti-apoptotic effect of BCL-2 protein resulting in release of cystolic mitochondrial cytochrome c of colon cancer human cells." (PMID 34069111, 2021). "BCL2 is highly expressed in many colon cancer patients to inhibit apoptosis." (PMID 33469000, 2021).